ICAM1 (intercellular adhesion molecule 1)
Diseases named in the same sentence as ICAM1 in open-access papers (continued):
Sharing a sentence is not in itself a finding about the gene and the disease.
infection (continued). "Twelve HRVs from species A bind to the minor receptors from the low density lipoprotein (LDL) receptor family, and the other 61 A-members as well as the B-viruses bind to intercellular adhesion molecule 1 (ICAM-1) for infection." (PMID 20937137, 2010). "As expected, the number of cells that are productively infected is enhanced when infection is performed with isogenic ICAM-1-bearing HIV-1 particles (i.e. NL4-3 ICAM-1+) resulting in more than 15% eGFP+ cells at five days post-infection." (PMID 19146679, 2009). "This suggests that the faster kinetics of infection with ICAM-1-bearing virions probably result in a faster return of gene expression to normal levels." (PMID 19146679, 2009). "Our study suggested that circulatory cytokines, namely, IL-4, IL-8, and adhesive molecules like ICAM-1 were enhanced after infection with C. pneumoniae whereas in contrast to this IL-10 and IFN-λwere lowered." (PMID 19360108, 2009). "In our experiments, the cell surface expression of ICAM-1 significantly increased after infection with both invasive and non-invasive NTHi isolates, demonstrating an activation of macrophages that may enhance their functions." (PMID 40137696, 2025). "Notably, in cells pre-incubated with 50 μg/mL of EVs, the transcriptional level of ICAM-1 was reduced to half of that observed in the S. suis-infection-only group." (PMID 41304154, 2025). "Although infection with two invasive NTHi strains did not cause noticeable differences in ICAM-1 or TNF-α expression, NTHi 08-252 induced higher IL-1β release." (PMID 40137696, 2025). "Our previous studies demonstrated that ICAM-1 is an important molecule present in BeWo cells used by T. gondii tachyzoites to adhere and invade these host cells, evidencing an important gateway to infection in the maternal–fetal interface." (PMID 40871442, 2025). "Another study proposed that RSV-infected airway epithelial cells upregulate the expression of intercellular adhesion molecule-1 (ICAM-1) on the cell surface, thereby creating a foundation for more severe human rhinovirus infection through ICAM-1, the principal receptor for human rhinovirus." (PMID 41333953, 2025). "Furthermore, we observed that in hCMEC/D3 cells, EMCV infection led to the upregulation of pSrc and enhanced its interaction with ICAM-1." (PMID 40631914, 2025). "Owing to the expression of chemokine receptors such as chemokine ligand 1 (CCL1), CCL18, and intercellular adhesion molecule-1 (ICAM-1) on M2-Exos, they can exhibit high recruitment of infection sites, thereby effectively solving the problem of poor targeting of existing Exos." (PMID 40177029, 2025). "To ascertain whether ICAM-1 regulates the Src-Ezrin-Cav-1 pathway via Src to jointly regulate EMCV internalization, we initially analyzed the viral titers in both wild-type (WT) BHK-21 cell lines and ICAM-1 KO BHK-21 cell lines following EMCV infection." (PMID 40631914, 2025). "Additionally, upon DENV infection, we observed a notable increase in ICAM-1 expression on day 4 post-infection." (PMID 40298772, 2025). "Our subsequent step will involve screening and comparing the protein interactome of Src before and after EMCV infection, with the aim of pinpointing crucial proteins that bridge ICAM-1 and Src, thereby providing deeper insights into the molecular mechanisms governing EMCV internalization." (PMID 40631914, 2025). "We assessed whether ICAM1 was truly upregulated by neutrophils upon infection with Gc or was upregulated due to the presence of other cell types present at low levels in our purified PMN population." (PMID 38976720, 2024). "In a human hBMECs in vitro BBB model, the meningitic E. coli PCN033 strain (at the multiplicity of infection (MOI)=10, ~ 108 colony-forming units (CFUs)) significantly upregulated the transcription of platelet-derived growth factor-B (PDGF-B) and ICAM-1, which reduces any accompanying infection." (PMID 38073104, 2024).
infection (continued). "We initially determined the level of ICAM1 during infection of HaCaT cells using a recombinant bacterial artificial chromosome (BAC)-derived VZV pOka strain expressing monomeric enhanced green fluorescent protein (GFP) under the control of the ORF57 promoter (pOka-Δ57-GFP)." (PMID 38909022, 2024). "This integrin is documented as essential for facilitating the adhesion and transmigration of neutrophils and monocytes to activated endothelium, primarily through ICAM-1 on the activated endothelial cells, thereby directing these immune cells to migrate toward sites of infection or inflammation." (PMID 38711712, 2024). "The infection of the HBMECs induces overexpression of surface adhesion molecules, intracellular adhesion molecule-1 (ICAM-1), vascular cellular adhesion molecule-1 (VCAM-1), VE-cadherin, N-cadherin, and β-catenin, and downregulates Occludin which is a tight junction membrane protein." (PMID 39840010, 2024). "The infection results in the upregulation of intercellular adhesion molecule-1 (ICAM-1) and vascular adhesion molecule-1 (VCAM-1) on ECs, along with integrins β1/β2, chemokines, and intracellular signaling pathway proteins, including Toll-like receptors (TLRs)." (PMID 39723133, 2024). "Infection with VZV expressing gC also led to enhancement of ICAM1 levels and T cell adhesion." (PMID 38909022, 2024). "Additionally, our study shows that hPEK exhibited heightened expression of various HLA class I molecules and immune relevant ligands such as PD-L1, PD-L2 and ICAM-1 after infection and treatment with recombinant IFN-γ." (PMID 39038032, 2024). "Taken together, these results suggest that the expression of immune cell adhesion molecules by SARS-CoV-2 activation, especially ICAM1, might continue even after the infection has been cleared." (PMID 39739157, 2024). "Notably, Fibronectin 1 (FN1), Toll-like receptor 2 (TLR2), and ICAM1 were involved in all three infection categories." (PMID 37233676, 2023). "ICAM-1 could be detected on EV but tended to be increased in EV from donors post-mild infection, which could lead to increased ability of this group to communicate with T cells via this route." (PMID 37520724, 2023). "The HA coating not only facilitates IMEs-targeting through interaction with intercellular-adhesion-molecule-1 on inflamed endotheliocytes, but also improves the biosafety of the nanosystem and enhances drug accumulation in primary infection sites triggered by hyaluronidase." (PMID 38161786, 2023). "Our data suggest that these two piRNAs predicted to target ICAM1 may in part contribute to the downregulation of ICAM1 transcript observed during early infection." (PMID 36936778, 2023). "Finally, protein–protein interaction analysis identified three primary proteins (ICAM1, TLR2, and FN1) associated with microbial infections mediating pro-inflammation, controlling infection, and facilitating microbial elimination." (PMID 37233676, 2023). "Strategies to prevent rhinovirus infection have included the use of recombinant soluble ICAM-1 as a decoy receptor able to inhibit infection or the use of a monoclonal anti-ICAM-1 antibody, which blocks binding of rhinovirus to ICAM-1 without preventing the interaction between ICAM-1 and LFA-1." (PMID 37237555, 2023). "The Omi-hyd-Dex@HA NPs could selectively accumulate in the infected tissues through HA/ICAM-1-mediated targeting effect and significantly decreased the mortality of sepsis mice by inhibiting infection and inflammation." (PMID 38161786, 2023). "Interestingly, inflammatory markers used in this study also displayed marked sex differences: peak NF-κB was higher in females and remained elevated on day 14 pi, whereas ICAM-1 rose to reach a plateau for the second week after infection." (PMID 37737732, 2023). "In contrast, infection with W83 only increased the AoSMC expression of Ccl2, Icam1, and Eng." (PMID 36483452, 2022).
infection (continued). "Nevertheless, the cDC2 subset was recruited at higher numbers to ICAM-1/2-/- LNs following PR8 infection, and were hyperactivated, as evident by their significantly elevated levels of the major co-stimulatory molecules CD80 and CD86, as well as elevated IL-6 production." (PMID 36895258, 2022). "For one, the infection of aortic lesions with P. gingivalis activates adhesion molecules such as intercellular adhesion molecule 1 (ICAM-1) and vascular cell adhesion molecule 1 (VCAM-1), leading to chronic inflammation via migration of more immune cells to the lesion sites." (PMID 35406643, 2022). "In order to follow the potential role of VCAM-1 in neutrophil and NK cell recruitment to PR8 infected lungs, we first verified that both leukocytes comparably expressed the main VCAM-1 binding integrin VLA-4 (α4β1) on their surface during active infection in both WT and ICAM-1/2-/- mice." (PMID 36895258, 2022). "Interestingly, while E-selectin allows weak binding of leukocytes to the endothelium and, therefore, their rolling towards the site of infection, s-ICAM1 induces strong binding, keeping the leukocytes at the site of infection to achieve its function." (PMID 35327327, 2022). "After three passages, which were needed to establish productive infections, all rhinoviruses tested could replicate efficiently on Vero_ICAM1#4C4." (PMID 36298792, 2022). "A Vero cell line that expresses both the ICAM1 and CDHR3 receptors could be constructed to obtain an HRV vaccine producer cell line susceptible to infection with all HRV serotypes." (PMID 36298792, 2022). "Persistent infection by coxsackie B viruses of human microvascular endothelial cells have been observed to result in increased expression of adhesion molecules, including ICAM1, especially shortly after the infection (<30-40 days after infection), fluctuating to lower levels afterwards." (PMID 35498413, 2022). "TNF-α, IL-1β, VEGFA, and ICAM-1 mRNA levels in tissues were detected, which were observed to be remarkably upregulated in the DR and DR + Lv-sh-NC groups whereas partially downregulated after Lv-sh-Cx43 infection." (PMID 36120455, 2022). "In addition, we show that within the peritoneal membrane lined by peritoneal mesothelial cells (PeM), the gene expression levels of cell adhesion markers VCAM-1 and ICAM-1 decrease significantly in response to a secondary infection." (PMID 35418979, 2022). "Another study further suggested ICAM1 as a potential prognostic indicator for COVD-19 infection." (PMID 35772218, 2022). "Moreover, our study investigated the morphological changes of the gills and skin tissues and the expression levels of the ICAM-1 gene in rainbow trout upon infection with IHNV, F. columnare, and I. multifiliis." (PMID 34489953, 2021). "Importantly, significantly higher expression levels of ICAM-1 were detected in mucosal tissues such as the skin and gills, especially at the early stages (i.e., 4 d and 7 d) of the infection." (PMID 34489953, 2021). "Some eosinophils in the lungs of both groups expressed ICAM-1 throughout the course of infection." (PMID 33673645, 2021). "Epithelial ICAM-1 thus promotes neutrophil recruitment and retention to the airway compartment, a response that may aid in pathogen clearance during infection but also exacerbates inflammation-mediated pathology." (PMID 33690714, 2021). "To summarize, the abnormal expression of CXCL10, ICAM1, CD40, IRF7, and B2M may be the main cause of tracheal dysfunction after infection with coronavirus." (PMID 34504502, 2021). "Thus, despite CVA21 being a human pathogen incapable of using murine ICAM-1 for infection, mice still generate an immune response to clear the virus." (PMID 34503272, 2021). "The adhesion molecule ICAM-1 was particularly upregulated upon LOAd703 infection." (PMID 33666760, 2021).
infection (continued). "Given that the bacterial burden in both Early and Early ΔlasR strains remained equivalent from the time of infection until day 4 p.i, the differences in ICAM-1 and inflammatory responses most likely resulted from differences in pathogen-host interactions rather than bacterial burden." (PMID 33690714, 2021). "Our results showed that the ICAM-1 gene was upregulated after infection in the four tissues." (PMID 34489953, 2021). "Moreover, insulin also increase the adhesion and hence migration of PMNs to the site of infection through upregulation of ICAM-1 in endothelium cells." (PMID 32915806, 2020). "Moreover, treatment with MLN4924 lead to recovered ICAM-1 RNA and protein production in Mavs–/–BMMs following infection with M. avium." (PMID 32463840, 2020). "In fact, MHC molecules as well as CD70 and ICAM-1 were rather downregulated upon LOAd infection in general, indicating that transcription levels may in some way be decreased due to the viral replication process." (PMID 32355275, 2020). "Infection was accompanied by an increased dose-dependent expression of its receptor, ICAM-1." (PMID 32637364, 2020). "The upregulation of ICAM-1 has been observed in in vitro infections with apicomplexan parasites." (PMID 31068227, 2019). "In addition to PDGF-BB, we also noted a significant induction of ICAM-1 in hBMECs in response to infection." (PMID 31092253, 2019). "De novo virus can subsequently be transferred to CD4+ T cells across the virological synapse, which uses adhesion factors such as intercellular adhesion molecular 1 (ICAM-1) to stabilize DC-T cell contacts, with infection being established more effectively than direct infection by free virus." (PMID 31156637, 2019). "ICAM-1 is now widely considered to be an important marker for endothelium activation, and its canonical function is widely believed to promote migration of leukocytes or monocytes to the infection site." (PMID 31092253, 2019). "A more clinically relevant study using ex vivo human tonsillar tissue corroborated the importance of ICAM-1 in increasing infection, whereby the advantages gained by virions bearing functionally active ICAM-1 were negated through the use of an anti-ICAM monoclonal antibody." (PMID 30669528, 2019). "Upregulation of ICAM1 early during infection and prior to PMN infiltration might indicate an additional role in signaling at this stage in addition to leukocyte trafficking." (PMID 29661181, 2018). "The fact that CD18 neutralizing antibody was not as efficient in blocking PMN adhesion to TNF-α treated BECs could be due to the excess level of ICAM-1 upregulated by TNF-α as compared to PUUV infection." (PMID 30283445, 2018). "In addition to vascular changes, ICAM-1 is crucial for neutrophil migration into the sites of infection through the vascular wall." (PMID 29849098, 2018). "While an increase in ICAM-1 density on the cell surface can enhance RV binding to improve infection rates, higher Gαi expression and lower cAMP level could then contribute to RV-induced airway hyperresponsiveness." (PMID 30373568, 2018). "When stimulating polyp epithelial cells with TNF-α, mimicking infection, ICAM1 was upregulated." (PMID 29367682, 2018). "Previous research has shown that HRV infection could upregulate ICAM-1-mRNA and inflammatory cytokines in submucosal gland cells, and, an anti-ICAM-1 antibody blocked both infection and production of these cytokines." (PMID 28056984, 2017). "In addition, we also used real-time qPCR to determine the mRNA expression of ICAM-1, miR-124 and MCP-1 in a swine lung injury caused by infection of porcine reproductive and respiratory syndrome virus (PRRSV)." (PMID 29340098, 2017). "The baseline ICAM‐1 mRNA expression in HNE cells obtained from allergic subjects was significantly higher than the baseline levels in the cells obtained from non‐allergic subjects prior to infection." (PMID 27957326, 2016).
infection (continued). "L‐Carbocisteine inhibits RV14 infection by reducing ICAM‐1 and acidic endosomes and may, therefore, modulate airway inflammation caused by RV infection in allergic subjects." (PMID 27957326, 2016). "The concentration of sICAM‐1 in the supernatants, the level of ICAM‐1 mRNA expression before infection, the RV14 viral titers, and RV14 RNA replication were higher in the cells obtained from the allergic subjects than in those obtained from non‐allergic subjects." (PMID 27957326, 2016). "Moreover, immunohistochemical analysis revealed markedly reduced staining of E-selectin and ICAM-1 in the brains of db/db mice when compared with WT mice at day 8 after infection." (PMID 24750819, 2014). "Under stressful conditions, such as hemorrhage, trauma, and infection, the expression and synthesis of ICAM-1 is upregulated rapidly, thereby inducing neutrophils to bind to vascular endothelial cells and exacerbate inflammatory response and microcirculation dysfunction." (PMID 24723822, 2014). "Therefore, the modest magnitude of virus-specific cytokine induction in these experiments was likely due to restriction of infection to the small subset of BE cells that express ICAM-1." (PMID 24219422, 2013). "14C11 did not inhibit CPE caused by infection with minor group serotype HRV25 consistent with ICAM-1 blockade-specific mechanism of action." (PMID 23935498, 2013). "Thus, trans infection is accentuated by interaction of various cell adhesion molecules such as LFA-1/ICAM-1 which are upregulated on activated mature DC and are involved in the DC-T cell virologic synapse." (PMID 24278768, 2013). "To test the effect of the anti-ICAM-1 antibody 14C11 in an in vivo major group HRV infection model, we challenged transgenic Balb/c mice over-expressing extracellular domain 1 and 2 of human ICAM-1 (tg+) and non-transgenic littermates (tg−) with major group HRV16." (PMID 23935498, 2013). "In situ, infection by major group HRVs leads to inflammation and increased ICAM-1 expression." (PMID 23227049, 2012). "In agreement with the observed reduction in neutrophils influx, mice receiving statins had a strong dose-dependent reduction in the protein levels of ICAM-1 present in the lungs prior to infection with S. pneumoniae (Control versus LSD, P = 0.04; Control versus HSD, P = 0.004)." (PMID 22587610, 2012). "ICAM-1 upregulation was significantly more enhanced after infection with S. suis strain 10 Δcps." (PMID 21592385, 2011). "Interestingly, expression of ICAM-1, which was shown to be involved in transfer infection of conventional monolayer epithelial cultures, was restricted to the apical surface of polarized cells." (PMID 21573183, 2011). "Our initial attempts to identify the cellular and viral components involved in synapse formation and transfer infection suggested an apparently critical role for B cell LFA-1/epithelial ICAM-1 interactions, at least in conventional monolayer cultures of primary epithelial cells." (PMID 21573183, 2011). "Furthermore, expression of several key host defense genes, including cytokines (TNFα and IL6) and bactericidal molecules, such as defensin-4 (NP4), NOS2, NOX1 and ICAM1, peaked only at 8 and/or 12 weeks post-infection." (PMID 22645653, 2011). "Since HIV gp120 has been shown to increase endothelial expression of ICAM-1 in vitro, we hypothesize that SIV-infection resulted in diffuse upregulation of ICAM-1 expression by myocardial endothelial cells." (PMID 21203448, 2010). "Interestingly, 28.5% of the genes modulated either by NL4-3 wt or NL4-3 ICAM-1+ at 8 h post-infection are still affected at the 24 h time point." (PMID 19146679, 2009). "We therefore tested whether CA17 infection was mediated by ICAM-1, using the prototype CA17-G12 and the isolate CA17.67591." (PMID 19412342, 2009).